CYP2D6 (cytochrome P450 family 2 subfamily D member 6 (gene/pseudogene))
Diseases named in the same sentence as CYP2D6 in open-access papers (continued):
Sharing a sentence is not in itself a finding about the gene and the disease.
Hepatic fibrosis (2 papers, 2011 to 2025). The presence of excessive fibrous connective tissue in the liver. "Another model using adenovirus vector containing human CYP2D6 infection of CYP2D6 transgenic mice had focal hepatocyte necrosis and hepatic fibrosis." (PMID 21760995, 2011). "An experimental study utilizing the CYP2D6 mouse model, which replicates several characteristic features of human AIH, such as interface hepatitis, hepatic fibrosis, and the formation of AIH-specific autoantibodies and CYP2D6-specific T cells, revealed that MASLD exacerbates AIH." (PMID 40694545, 2025).
hypoglycaemia (2 papers, 2022 to 2023). "After 1 month of treatment, the occurrence of hyperkalaemia and hypoglycaemia were not related to β1-AR mutation or CYP2D6 188C>T." (PMID 35586822, 2022). "The β1-AR mutation and CYP2D6 188C>T were not correlated with hyperkalaemia and hypoglycaemia after 1 month of treatment." (PMID 35586822, 2022).
Hyponatremia (2 papers, 2023 to 2024). An abnormally decreased sodium concentration in the blood. "For instance, low-activity CYP2D6 genotypes have been associated with an increased risk of hyponatremia and increased cortisol production when MDMA is used." (PMID 39204437, 2024). "Indeed, as for low CYP2D6 activity genotypes, low COMT activity genotypes have been associated with an increased risk of hyponatremia and increased production of cortisol." (PMID 39204437, 2024).
influenza (2 papers, 2014 to 2020). An acute viral infection of the respiratory tract, occurring in isolated cases, in epidemics, or in pandemics; it is caused by serologically different strains of viruses (influenzaviruses) designated A, B, and C, has a 3-day incubation period, and usually lasts for 3 to 10 days. "The encounter-based CDS helped providers choose and implement the correct guideline-based medications for different scenarios (corticosteroid for worsening COPD, cefepime when hospitalized for COPD, hydrocodone vs codeine based on CYP2D6 genotype, influenza vaccine on hospital discharge)." (PMID 33064106, 2020).
ovarian carcinoma (2 papers, 2016 to 2022). A malignant neoplasm originating from the surface ovarian epithelium. "It is unclear how the mutation in CYP2D6 could impact clinical outcome after NACT in patients with ovarian cancer, as carboplatin is excreted primarily by kidneys and paclitaxel is metabolized mainly by cytochromes P450 2C8 and 3A4." (PMID 35501919, 2022).
overdose (2 papers, 2022 to 2025). An excessive and dangerous dose of a drug. "Is concomitant use of oxycodone with selective serotonin reuptake inhibitors (SSRIs) that are potent inhibitors of oxycodone metabolism via the cytochrome-P450 2D6 (CYP2D6) enzyme (fluoxetine and paroxetine) associated with opioid overdose?" (PMID 35201310, 2022).
schistosomiasis (2 papers, 2016 to 2017). An infectious disease caused by parasitic trematodes of the genus Schistosoma that colonize human blood vessels and release eggs that can cause granulomatous reactions leading to acute (swimmer's itch or acute schistosomiasis syndrome) or chronic disease. "In contrast, we found that 4 of 14 (28.5%) schistosomiasis-haematobia-infected patients are carriers of the inactivated allele CYP2D6*5, which is characterized by a deletion of the entire CYP2D6 gene." (PMID 29182577, 2017). "Importantly, the frequency of poor metabolizer CYP2D6 alleles is low in schistosomiasis endemic regions such as Africa, South America, Middle East." (PMID 27518281, 2016). "This preliminary study with a limited number of patients suggested that CYP2D6 *5/*5 and IL6-174C polymorphisms has an effect on severity and morbidity of schistosomiasis." (PMID 29182577, 2017). "In the present study, we found that 28.5% of schistosomiasis-infected patients were carriers of CYP2D6 *5/*5." (PMID 29182577, 2017).
steatosis (2 papers, 2021 to 2022). Increased lipid within the cytoplasm of cells. "The objective of our work was to study the impact of periportal steatosis on pericentral drug metabolism focusing on the important CYP isoforms CYP1A2, CYP2D6, CYP2E1, and CYP3A4." (PMID 36528753, 2022). "Periportal steatosis did also affect the pharmacokinetics of caffeine (CYP1A2) and midazolam (CYP3A4), but not of codeine (CYP2D6)." (PMID 36528753, 2022).
Stroke (2 papers, 2025 to 2026). Sudden impairment of blood flow to a part of the brain due to occlusion or rupture of an artery to the brain. "Carriers of sensitive genotypes for AGTR1, CYP2D6*10, and ADRB1 taking sensitive drugs exhibited a significantly lower risk of stroke (ORs: 0.39, 0.67, 0.68; all P < 0.01)." (PMID 41968188, 2026).
systemic lupus erythematosus (2 papers, 2020 to 2023). An autoimmune multi-organ disease typically associated with vasculopathy and autoantibody production. "Systemic lupus erythematosus patients carrying CYP2D6 variants might be considered at risk for certain manifestations of SLE." (PMID 36940959, 2023). "A study investigating the relationship between polymorphisms of Cytochrome P450 2D6 and blood hydroxychloroquine levels in patients with systemic lupus erythematosus showed that patients with rs1135840 G/G homozygotes had decreased CYP2D6 activity and lower concentrations of metabolites." (PMID 32219146, 2020). "Additionally, the knowledge of CYP2D6 polymorphism in SLE may help establish a recommendation for considering genetic markers in optimizing care and therapy for lupus patients, particularly in the case of specific organ involvement." (PMID 36940959, 2023).
Tremor (2 papers, 2017 to 2019). An unintentional, oscillating to-and-fro muscle movement about a joint axis. "In addition, there was a trend to an earlier age of PD onset and a tremor dominant phenotype in CYP2D6*4 variant carriers." (PMID 28680508, 2017). "However, this generalization is not absolute due to hyperhidrosis and tremor showing bias toward CYP2D6." (PMID 31616600, 2019).
vitamin D deficiency (2 papers, 2013 to 2020). A nutritional condition produced by a deficiency of VITAMIN D in the diet, insufficient production of vitamin D in the skin, inadequate absorption of vitamin D from the diet, or abnormal conversion of vitamin D to its bioactive metabolites. "CYP2D6 is a potential 25 hydroxyvitamin D-1 α-hydroxylase, which converts vitamin D3 into 25OHD, and vitamin D 25-hydroxylase deficiency resulted in vitamin D deficiency.Human 25-hydroxyvitamin D-1 α-hydroxylase mutations also cause vitamin D-dependent rickets type 1." (PMID 24171052, 2013). "Moreover, CYP2D6 is a potential 25 hydroxyvitamin D-1 α-hydroxylase, which converts vitamin D3 into 25OHD, and vitamin D 25-hydroxylase deficiency resulted in vitamin D deficiency." (PMID 24171052, 2013).
α-thalassaemia (2 papers, 2020 to 2023). "The results of the multivariate regression analyses, which were performed using βS haplotypes and α-thalassemia, as well as some laboratory biomarkers as confounding variables, confirmed the independent association of CYP2D6 1934G>A, CAT -21A>T, and -262C>T with several of these parameters." (PMID 33013391, 2020).
acromegaly (1 paper, 2019). Acromegaly is an acquired disorder related to excessive production of growth hormone (GH) and characterized by progressive somatic disfigurement (mainly involving the face and extremities) and systemic manifestations. "Its is well established that hyperhidrosis, as found ranked 5th in CYP2D6 transcript abundance, is often seen in patients suffering from acromegaly." (PMID 31616600, 2019).
acute leukemia (1 paper, 2020). A clonal (malignant) hematopoietic disorder with an acute onset, affecting the bone marrow and the peripheral blood. "Recently, associations between childhood acute leukemia (CAL) and genetic polymorphism of CYP2D6*4 for homozygous alleles were reported, suggesting CYP2D6*4 polymorphism could play a vital role in the etiology of CAL." (PMID 33192522, 2020).
alcoholic liver diseases (1 paper, 2021). A disorder caused by damage to the liver parenchyma due to alcohol consumption. "Alcoholic liver disease and primary biliary cholangitis were involved in the most prominent changes in the protein abundances, with downregulation of 6 (CYP1A2, CYP2C8, CYP2D6, CYP2E1, CYP3A4, UGT2B7) and 5 (CYP1A1, CYP2B6, CYP2C8, CYP2E1, CYP3A4) significantly downregulated enzymes, respectively." (PMID 34575411, 2021).
anorexia nervosa (1 paper, 2020). A disorder most often seen in adolescent females characterized by a refusal to maintain a minimally normal body weight, an intense fear of gaining weight, a disturbance in body image, and, in postmenarcheal females, the development of amenorrhea. "In this study, 24 patients with anorexia nervosa at two occasions ingested single oral doses of five test drugs known to be metabolized by CYP1A2, CYP2C9, CYP2C19, CYP2D6, and CYP3A4, respectively." (PMID 32529756, 2020). "For CYP1A2, CYP2C9, CYP2C19, and CYP2D6, there are no studies on enzyme activities in anorexia nervosa or otherwise underweight subjects." (PMID 32529756, 2020). "Due to the lack of information on the possible effect of low body weight on most CYP enzymes, the aim of this study was to explore whether changes in body weight in patients with anorexia nervosa affect the metabolic activity of the CYP enzymes CYP1A2, CYP2C9, CYP2C19, CYP2D6, and CYP3A4." (PMID 32529756, 2020).
bowel dysfunction (1 paper, 2025). Any disease in which the causes of the disease is a perturbation of the lower digestive tract leading to its dysfunction. "Biomarker research investigating genetic polymorphisms in drug-metabolizing enzymes (CYP2D6, CYP3A4) and neurotransmitter receptors could identify patients at highest risk for developing medication-induced bowel dysfunction, enabling personalized medicine approaches." (PMID 41327232, 2025).
Brugada syndrome (1 paper, 2020). A genetically heterogeneous condition characterized by complete or incomplete right bundle branch block accompanied by ST elevation in leads V1-V3. "Reduce the dose to 75% of the standard dose for CYP2D6 intermediate metabolizer (IM) patients with indications other than the diagnosis of Brugada syndrome and record an ECG and monitor the plasma concentration." (PMID 32378381, 2020).
candidiasis (1 paper, 2020). Infection with the organism Candida. "Overall, (S)-8g had a pharmacological profile to pursue further biological investigations such as a murine candidiasis assay and cytochrome P450 inhibition assays (e.g. CYP3A4, CYP2D6)." (PMID 32784450, 2020).
catalepsy (1 paper, 2021). A nervous system disorder characterized by diminished responsiveness and consciousness, and rigidity of the body. "They show that lower CYP2D6 activity in the brain decreases the risk for catalepsy and VCM development, whereas high CYP2D6 activity increases VCM and catalepsy development." (PMID 35140610, 2021).
cholestasis (1 paper, 2018). Impairment of the bile flow caused by obstruction within the liver, or outside the liver in the bile duct system. "Ethinylestradiol, a female hormone that is known to cause cholestasis when administered at a high dose, also repressed hepatic CYP2D6 expression in CYP2D6-humanized mice." (PMID 29673183, 2018).
chronic hepatitis C (1 paper, 2021). "It now appears that CYP2D6 activity is not modulated by inflammation and this is confirmed in chronic hepatitis C patients where downregulation is linked to the presence of liver kidney microsomal type 1 (LKM-1) antibodies." (PMID 34867341, 2021).
congestive heart failure (1 paper, 2021). Failure of the heart to pump a sufficient amount of blood to meet the needs of the body tissues, resulting in tissue congestion and edema. "In addition, one study showed that inflammatory markers were inversely correlated with CYP1A2 and CYP2C19 activity but not with CYP2D6 and CYP2E1 activity in patients with congestive heart failure." (PMID 34867341, 2021).
dengue (1 paper, 2025). "CYP2D6 mediates the metabolism of approximately 25% of marketed drugs, and its inhibition could affect co-administered medications commonly used in dengue management, including analgesics and antiemetics." (PMID 41471395, 2025).
fibromyalgia (1 paper, 2025). A chronic disorder of unknown etiology characterized by pain, stiffness, and tenderness in the muscles of neck, shoulders, back, hips, arms, and legs. "Genetic predispositions in CYP2D6 and catechol-O-methyltransferase contribute to high pain sensitivity and analgesic therapy failure in a fibromyalgia patient, suggesting the need for further study." (PMID 39995492, 2025).
gastric cancer (1 paper, 2022). A primary or metastatic malignant neoplasm involving the stomach. "The association of CYP2D6 genotypes with the dose of tramadol consumed within 48 h was explored in a prospective study conducted among 70 Chinese gastric cancer patients treated with tramadol post-gastrectomy." (PMID 36422103, 2022).
Headache (1 paper, 2021). Cephalgia, or pain sensed in various parts of the head, not confined to the area of distribution of any nerve. "Syncope was associated linearly with CYP2D6 saturation/inhibition (p = 0.050, and OR 1.42 [1.02–1.98]), while headache was again reversely associated with CYP2D6 saturation/inhibition (p < 0.001, and OR 0.38 [0.26–0.55])." (PMID 34025403, 2021). "However, headache correlated reversely with CYP2D6 activity in the total population with higher activity associated with less drug-related headache." (PMID 34025403, 2021).
immunotoxicity (1 paper, 2024). "In parallel, the standard drug Clomiphene citrate underwent scrutiny for its ADMET properties, revealing its role as a CYP2D6 inhibitor and its potential to induce immunotoxicity." (PMID 39660761, 2024).
Infantile hemangiomas (1 paper, 2020). "The aim of this study is to evaluate the association of genetic polymorphisms in Cytochrome P450 2D6(CYP2D6) and the change in VEGF levels with the response to propranolol in patients with Infantile hemangiomas (IH)." (PMID 32219146, 2020).
infiltrating ductal carcinoma (1 paper, 2019). "This is similar to results in previous studies in which the highest endoxifen concentrations were identified and correlated with different allelic forms of CYP2D6 in patients with infiltrating ductal carcinoma." (PMID 30792473, 2019).
inflammatory bowel disease (1 paper, 2022). A spectrum of small and large bowel inflammatory diseases of unknown etiology. "In addition, data have been published that “fast” alleles of the CYP2D6 gene are more common in patients with inflammatory bowel diseases." (PMID 35625789, 2022).
Insulin resistance (1 paper, 2025). Increased resistance towards insulin, that is, diminished effectiveness of insulin in reducing blood glucose levels. "In a cohort of children with ASD with insulin resistance, CYP2D6 genotypes do not influence plasma Risperidone concentrations." (PMID 41009999, 2025).
intrahepatic cholestasis (1 paper, 2022). A cholestasis characterized by impairment of the bile flow caused by obstruction located in the liver. "In conclusion, our case highlighted that severe intrahepatic cholestasis associated with dacomitinib hepatotoxicity warranted more awareness, and drug interactions should be monitored, especially liver metabolic enzymes CYP2D6 were involved." (PMID 35801736, 2022). "Dacomitinib-induced liver injury is often manifested by mild elevations of transaminases and bilirubin, and severe intrahepatic cholestasis caused by dacomitinib for simultaneous taking orally cytochrome P450 2D6 (CYP2D6) competitive substrates has been rarely reported." (PMID 35801736, 2022).
lactic acidosis (1 paper, 2022). Metabolic acidosis characterized by the accumulation of lactate in the body. "The risk of lactic acidosis is also increased by CYP2D6 gene mutations that lead to high levels of unmetabolized phenformin." (PMID 35804992, 2022). "Third, alterations of the enzymes that metabolize phenformin (CYP2D6 and P-glycoprotein) can modulate phenformin circulating levels and consequentially the risk of lactic acidosis." (PMID 35804992, 2022).
large cell lung carcinoma (1 paper, 2019). "We found the expressions of CYP2D6 were significantly up‐regulated in large cell lung carcinoma, AC and SCC patients compared with the normal samples (P < 0.05), and CYP24A1 and CYP20A1 were found overexpressed in the AC (P < 0.05)." (PMID 31264381, 2019).
long-QT syndrome (1 paper, 2021). "Antidepressants have a variety of side effects (e.g., long-QT syndrome), drug interactions (e.g., inhibition of CYP2D6), and contraindications (e.g., parallel use of monoamine oxidase inhibitors) must be considered, none of which are important with ambroxol." (PMID 33895135, 2021).
major depressive episode (1 paper, 2023). "A study performed in 45 patients with major depressive episodes found that in non-smokers, the plasma levels of mirtazapine and its metabolites depended on the CYP2D6 genotype." (PMID 36983567, 2023).
malnutrition (1 paper, 2021). Inadequate nutrition resulting from poor diet, malabsorption, or abnormal nutrient distribution. "However, the omission of malnutrition and CYP2D6 metabolizer status is no different from current dosing, and the proposed dosing regimen suggested here will not augment these limitations." (PMID 34503519, 2021).
Meconium ileus (1 paper, 2022). Obstruction of the intestine due to abnormally thick meconium. "It is likely that the ontogeny of the CYP2D6 gene contributes to the development of meconium ileus in patients with CF." (PMID 35625789, 2022). "Our results indicate that the presence of slow CYP2D6*4 alleles is more common in the group of patients without meconium ileus; the development of this syndrome may be directly related to the presence of functional alleles of the CYP2D6*4 gene." (PMID 35625789, 2022).
memory impairment (1 paper, 2019). "Whereas, SSRIs that are substrates of CYP2D6 have ADRs related to cognition that range from nightmares to memory impairment." (PMID 31616600, 2019).
methamphetamine dependence (1 paper, 2012). A drug dependence that is a psychological dependency on the regular use of methamphetamine. "A significant association of the CYP2D6 genotype with methamphetamine dependence (p = 0.03) was reported." (PMID 23162568, 2012). "Among these genes was CYP2D6 which was associated with methamphetamine dependence." (PMID 23162568, 2012). "Of particular relevance was a report in which a total of 202 patients with methamphetamine dependence and 337 controls in a Japanese population were genotyped for CYP2D6*1, *4, *5, *10, and *14." (PMID 23162568, 2012). "A potential conclusion of this study is that a lower CYP2D6 activity seems to confer some degree of protection against methamphetamine dependence." (PMID 23162568, 2012).
morbid obesity (1 paper, 2019). An excess of body weight, normally defined as an individual with a body mass index greater than 35 or a body weight greater than one hundred percent of ideal body weight. "It is worth noting that both CYP3A4 and CYP2D6 activities are altered in morbid obesity although they follow different patterns (the first is decreased whereas the second is increased)." (PMID 31892725, 2019).
Neurodevelopmental delay (1 paper, 2025). "Polymorphisms in CYP3A4, CYP2C19, and CYP1A2 could impair detoxification of environmental toxicants, while dysfunction in CYP2E1 and CYP2D6 has been linked to oxidative stress and mitochondrial impairment—both implicated in neurodevelopmental delays." (PMID 40386062, 2025).
neurotoxicity (1 paper, 2011). Toxicity that causes injury to the central or peripheral nervous system or damages its function. "In contrast, the Asian patient with CYP2D6*10*10 polymorphism, with partially decreased enzyme activity, developed neurotoxicity syndrome two weeks after treatment initiation." (PMID 22389859, 2011).